APOC1 (apolipoprotein C1)
Diseases named in the same sentence as APOC1 in open-access papers (continued):
Sharing a sentence is not in itself a finding about the gene and the disease.
dyslipidemia (16 papers, 2011 to 2025). "The association between APOE and APOC1 variants and metabolic syndrome and serum albumin levels further supported the crucial role of APOE region variants in cardiometabolic disorders in a Taiwanese population." (PMID 36011277, 2022). "In men with metabolic syndrome, elevated apoC1 levels were also associated with higher TG levels but lower visceral fat mass." (PMID 36471375, 2022). "Our data also indicated that APOE and APOC1 variants were independently associated with metabolic syndrome and serum albumin levels, respectively." (PMID 36011277, 2022). "A first study was conducted in patients with metabolic syndrome and demonstrated that high plasma levels of apoC1 were associated with increased carotid wall thickness only in the subgroup presenting with systemic inflammation (hsCRP > 3 mg/L)." (PMID 36471375, 2022). "APOE rs429358 and APOC1 rs438811 were also independently associated with metabolic syndrome (p = 2.29 × 10−14) and serum albumin levels (p = 3.80 × 10−6), respectively." (PMID 36011277, 2022). "Raised levels of apoC1 were also detected in individuals with cardiovascular risk, such as men with metabolic syndrome, or women, either with polycystic ovarian syndrome or post-menopausal with increased body mass index." (PMID 31779116, 2019). "Metabochip genotype array analysis of an African-American population identified 27 SNPs associated with the metabolic syndrome; however, only one (APOC1) was associated with all five components of the metabolic syndrome." (PMID 27312935, 2016). "Another SNP, rs4420638, an A→G transition of nucleotide, located about 340 bp downstream of the 3’ terminus of the apoC1 gene, tags a linkage desequibrium (LD) block involving the TOMM40, apo E, and apoC1 genes, and has been implicated in dyslipidemia." (PMID 41356011, 2025). "In addition, apoB was positively correlated with hypertension and dyslipidemia, whereas apoC1 was also positively correlated with hypertension." (PMID 36551995, 2022). "A second class consisted of carrier proteins such as apolipoprotein M (APOM), apolipoprotein C1 (APOC1), and clusterin (CLU), which play important roles in cholesterol metabolism and are likely to be associated with cirrhosis‐related dyslipidemia due to reduced liver biosynthesis capacity." (PMID 30824564, 2019). "Moreover, in male patients with metabolic syndrome, a correlation was established between the levels of apoC1 and apoC3 in plasma and the diminution of corporal adiposity." (PMID 31779116, 2019). "In addition, APOC1 is the only known endogenous cholesteryl ester transfer protein inhibitor, and this constitutive effect of APOC1 is impaired in coronary artery disease with dyslipidemia." (PMID 35370712, 2022). "Their complicated functions were specified by comparing DEGs in PMN versus Ctrls: first, PMN samples showed increased expression levels of APOC1 and APOE in response to dyslipidemia in PMN." (PMID 38785168, 2024).
gastric cancer (15 papers, 2010 to 2024). A primary or metastatic malignant neoplasm involving the stomach. "Two studies dealing with gastric cancer found higher ApoC1 serum levels to be associated with a better prognosis." (PMID 36216850, 2022). "In contrast, another recent publication described the tumor burden in gastric cancer to be elevated in the presence of higher ApoC1 levels." (PMID 36216850, 2022). "In gastric cancer, abnormal expression of APOC1 can predict the clinical characteristics and unfavourable prognosis of patients." (PMID 34857818, 2021). "Third, APOC1 commonly up regulated in gastric cancer compared to normal gastric epithelium, is already considered as a possible biomarker for gastric cancer." (PMID 21931799, 2011). "Additionally, there have been reports indicating that APOC1 promotes the progression of gastric cancer and the proliferation of prostate cancer." (PMID 38515073, 2024). "Other studies claim that APOC1 is overexpressed in gastric cancer." (PMID 38067270, 2023). "In one study, it was shown that APOA2, APOC1, and fibrinogen a-chain were distinguishing biomarkers that could diagnose gastric cancer." (PMID 38067270, 2023). "In gastric cancer (GC), APOC1 revealed the value of diagnosing and prognosing for GC." (PMID 32974161, 2020). "Furthermore, APOC1 has been found to promote the development of gastric cancer." (PMID 38515073, 2024). "Additionally, APOC1 expression was distinctly higher in gastric cancer and had a close relationship with some tumour prognostic indicators, such as clinical stage, tumour classification, lymph node metastasis and shorter overall survival and relapse-free survival." (PMID 34857818, 2021). "In gastric cancer, long non-coding RNA deleted in lymphocytic leukemia 1 (DLEU1) binds to SMYD2 and translocates to the apolipoprotein C1 (APOC1) gene promoter." (PMID 39482529, 2024). "Another study demonstrated that zinc finger protein 460 can promote APOC1 transcription, accelerating the epithelial–mesenchymal transition (EMT) and the development of gastric cancer." (PMID 38067270, 2023). "Of these 12 genes, 7 genes highly expressed in gastric cancer tissues were down-regulated (ITGB5, TYMS, MYB, APOC1, CBX5, PLA2G2A, KIF20A) and 5 low-expressed genes were up-regulated after vorinostat treatment (SCGB2A1, TCN1, CFD, APLP1, NQO1." (PMID 21931799, 2011). "Expression of ITGB5, TYMS, MYB, APOC1, CBX5, PLA2G2A, and KIF20A which is up-regulated in human gastric cancer tissues, was significantly decreased by vorinostat." (PMID 21931799, 2011). "Moreover, gene expression analysis of gastric cancer identified a collection of genes (ITGB5, TYMS, MYB, APOC1, CBX5, PLA2G2A, and KIF20A) whose expression was elevated in gastric tumor tissue and downregulated more than 2-fold by vorinostat treatment in gastric cancer cell lines." (PMID 21931799, 2011).
lung carcinoma (15 papers, 2014 to 2024). "Apoc1 has now been linked to lung cancer, kidney cancer, and gastrointestinal malignancies in a number of studies." (PMID 36242090, 2022). "A recent study reported that APOC1 was highly expressed in late‐stage lung cancer tissues 34 and was proposed as one of the diagnostic and prognostic biomarkers for lung cancer." (PMID 29148252, 2018). "ApoC1 is a promising biomarker for diagnosing lung cancer and the underlying relationship between ApoC1 and IL-6, which may be explored to find novel therapies." (PMID 36506554, 2022). "In a marker phase I trial, ApoC1 in tumor tissue is highly expressed in late-stage lung cancer and the over-expression is positively correlated with interleukin-6 (IL-6), a molecule that can foster lung cancer cell proliferation." (PMID 36506554, 2022). "APOC1 is one of three genes whose expression levels are predictive of diffuse large B-cell lymphoma severity, and it is also upregulated in late stage lung cancers as compared to early stage lung cancers." (PMID 36873459, 2022). "The key role of apolipoprotein C-1 (ApoC-1) is reported in breast, pancreas and lung cancer." (PMID 36381193, 2022). "Moreover, in mice that overexpress APOC1, levels of IL-6 and IL-1 beta are elevated, and in lung cancer patients." (PMID 29541006, 2018). "For example, inhibition of apolipoprotein C1 (APOC1) restores ferroptosis sensitivity, leading to the conversion of tumor-associated macrophages from an M2 to an M1 phenotype and enhancing anti-PDCD1 immunotherapy against hepatocellular carcinoma and lung cancers." (PMID 38844964, 2024). "ApoC-1 as a surface component of lipoproteins including chylomicron, HDL and LDL is mainly expressed in liver and its oncogenic role has been reported in pancreatic, breast and lung cancer." (PMID 36381193, 2022).
COVID-19 (14 papers, 2020 to 2024). A disease caused by infection with severe acute respiratory syndrome coronavirus 2. "Apolipoprotein C1 (APOC1) had a low level in the critical patients, suggesting that APOC1 was associated with the severity of COVID-19." (PMID 35911765, 2022). "The majority of the proteins associated with cholesterol metabolism, including APOC1, APOH, and APOE, were found to be decreased, except for APOA4, which was elevated in COVID-19 patients." (PMID 38672194, 2024). "There was also downregulation of lipid metabolism-associated genes (FABP4, APOC1, APOE, MARCO) in COVID-19 effector CD8+Tcs." (PMID 37029220, 2023). "Recently, a panel of five proteins with downregulated expression, namely, albumin (ALB), apolipoprotein A1 (APOA1), apolipoprotein C1 (APOC1), gelsolin (GSN), and transferrin (TF), was identified as a core signature associated with the severity of COVID-19." (PMID 34471261, 2021). "Patients with devere and mild COVID-19 exhibited substantial reduction in the expression of FABP4, APOC1, APOE, C1QB, and NURP1, all associated with interstitial and macrophage cluster-0." (PMID 33138195, 2020). "Other studies have shown a renoprotective role of linagliptin in animal models by modifying different signaling pathways (collagen type I homeostasis, HNRNPA1, YB-1, thymosin β4 and TGF- β1 and apolipoprotein C1), which could be also involved in the beneficial effect in COVID-19 patients." (PMID 35017617, 2022). "This protein is part of the “statin inhibition of cholesterol production”, that was in our study mediated by upregulated proteins (including the apolipoprotein C-I, APOC1) in COVID-19 patients." (PMID 39594201, 2024). "Although the cholesterol metabolism pathway was significantly downregulated (including APOA2, APOC1, APOH, CETP, and APOA4), the increased levels of PCSK9 and APOB suggested the dysregulation of cholesterol metabolism in severe and critical COVID-19 patients." (PMID 35958562, 2022). "Interestingly, although macrophages were also present in healthy subjects and patients with mild COVID-19, they had different gene signatures, indicative of interstitial and cluster-0 macrophage (i.e., FABP4, APOC1, APOE, C1QB, and NURP1)." (PMID 33138195, 2020). "In particularwe observed a decrease in the HDL components APOA4 and APOC1 in both COVID-19 non-ICU and ICU/F patients (cluster 3) while APOA2, APOD, APOH, APOM and the HDL-associated PON1 protein appear to be decreased mainly in COVID-19 non-ICU patients (cluster 7)." (PMID 36348270, 2022).
coronary artery disease (11 papers, 2013 to 2025). "Putative TFs for SNPs rs55730499 of LPA, rs4420638 of APOC1, and rs3136441 of F2 were subjects of great interest because these loci were associated with coronary artery disease." (PMID 35203469, 2022). "In a prospective study in more than 2767 subjects, the analysis of additional polymorphisms at the apoC1 gene evidenced a slight effect on coronary heart disease." (PMID 36471375, 2022). "Polymorphisms of APOC1 (p = 0.01), F2 (p = 8 × 10−8), LPA (p = 0.001), and PLTP (p = 0.0009) showed significant individual effects on the predisposition to coronary artery disease." (PMID 35203469, 2022). "At present, ApoC1 is the only known endogenous inhibitor of cholesteryl ester transfer protein, and this constitutive action of apoC1 is impaired in coronary artery disease of dyslipidemic patients." (PMID 31779116, 2019). "However, its locus has been extensively linked to coronary artery disease (neighboring genes are APOE, APOC1, and TOMM40)." (PMID 29527417, 2018). "Thus, the APOC1 genotype may serve as a valuable predictor of APOE status and independently impact LDL cholesterol concentrations, C-reactive protein levels (a common inflammation biomarker), and coronary heart disease risk." (PMID 40722932, 2025). "The present study is the first to show that lipid-associated GWAS loci such as rs4420638 of APOC1, rs3136441 of F2, rs55730499 of LPA and rs6065906 of PLTP are susceptibility markers for coronary artery disease regardless of sex, age, and body mass index." (PMID 35203469, 2022). "We found that four polymorphisms such as rs4420638 of the APOC1 gene, rs3136441 of the F2 gene, rs55730499 of the LPA gene, and rs6065906 of the PLTP gene were significantly associated with the risk of coronary artery disease regardless of sex, age, and body mass index." (PMID 35203469, 2022).
dementia (11 papers, 2018 to 2025). Loss of intellectual abilities interfering with an individual's social and occupational functions. "Meanwhile, the SNP rs445925 in gene APOC1 can be detected only by the SIR method, and APOC1 gene is reported to be a genetic risk factor for dementia and cognitive impairment in the elderly and it has a significant impact on hippocampal volumes." (PMID 38575890, 2024). "The presence of unfavorable alleles, e.g., in APOE cluster, TOMM40 or APOC1 is known to facilitate the dementia onset under oxidative stress." (PMID 30443289, 2018). "Other genes previously associated with AD or dementia were differentially expressed in both brain regions: CHI3L2, FCGBP, GLI1, STAB1, APOC1, MYO7A, and long non‐coding RNA JHDM1D‐AS1." (PMID 39876821, 2025). "Dozens of significant dementia-associated genes have been identified, including APOE, APOC1, and TOMM40." (PMID 38542318, 2024). "APOC1 is highly expressed in younger patients with dementia and diabetic nephropathy, and in the aqueous humor of diabetic retinopathy patients with type 2 diabetes." (PMID 39081806, 2024). "However, a case–control GWAS (with family history of dementia as exclusion criteria in cases) with 9 of 13 significant SNPs in the APOE region implicated APOE, APOC1, TOMM40, and NECTIN2 in the prediction of clinical diagnosis of AD in the Chinese population." (PMID 40352683, 2025). "APP, APOC1, APOE, SORL1, and MAPT are highly relevant common genes for AD and dementia." (PMID 38790243, 2024). "Significantly associated proteins at a false discovery rate (FDR) < 0.05 in both models 1 and 2 were CGREF1, MET, ALDH2, NECTIN2, APOC1, APOE and FOSB for HFRS, and CDK and POF1B for HFRS without dementia." (PMID 40764432, 2025).
prostate carcinoma (11 papers, 2014 to 2025). A carcinoma that arises from epithelial cells of the prostate gland. "One study reported an increase in serum APOC1 protein levels in patients during disease progression, suggesting an association with prostate cancer progression." (PMID 38067270, 2023). "Suppressing APOC1 significantly reduces prostate cancer cell growth and colony formation, while its overexpression enhances glioblastoma cell proliferation, migration, and invasion." (PMID 39873475, 2025). "In our study, we identified AOX1, APOC1, ARMCX1, FLRT3, GSTM2, and HPN as biomarkers associated with prostate cancer (PCa)." (PMID 37583929, 2023). "APOC1 mediates the cell survival, cell cycle distribution, and apoptosis of prostate cancer via activating the survivin/Rb/p21/caspase-3 signaling pathway." (PMID 38067270, 2023). "The possible prostate cancer (PCa) diagnostic biomarkers AOX1, APOC1, ARMCX1, FLRT3, GSTM2, and HPN were identified and validated using the GSE69223 and GSE71016 datasets." (PMID 37583929, 2023). "The upregulated mRNA and protein expression levels of ApoC-1 in prostate cancer tissue is correlated with survival of prostate cancer cells by inhibiting apoptosis, also the increased serum level of ApoC-1 is associated with the prognosis of prostate cancer patients." (PMID 36381193, 2022). "APOC1 was demonstrated to promote cell proliferation in prostate cancer cells in vitro." (PMID 32974161, 2020). "However, the exact role of APOC1 in prostate cancer pathogenesis remains unclear." (PMID 38067270, 2023).
type 2 diabetes (11 papers, 2015 to 2024). "APOC1 concentrations were higher in patients with type 2 diabetes and significantly positively correlated with plasma TG levels, and not visceral adipose tissues." (PMID 37448184, 2023). "Differences in plasma APOC1 levels have also been previously reported in the context of type 2 diabetes and in relation to nutrition." (PMID 37743383, 2023). "For instance, the A-allele of the SNP rs4420638 in the APOC1 locus increases serum CRP levels and is associated with a lower risk of type 2 diabetes." (PMID 25768928, 2015). "In patients with type 2 diabetes, the elevated serum triglyceride levels negatively correlate with circulating LPL levels, and positively with circulating APOC1, APOC3, ANGPTL3, ANGPTL4 and ANGPTL8 levels." (PMID 37448184, 2023). "Both APOC1 and APOC3 inhibit LPL activation, and the circulation levels are investigated in patients with type 2 diabetes." (PMID 37448184, 2023).